MEN1 (menin 1)
Diseases named in the same sentence as MEN1 in open-access papers (continued):
Sharing a sentence is not in itself a finding about the gene and the disease.
insulinomas (continued). "In about 10% of patients, insulinoma can be associated with MEN1 and very infrequenty with Von Hippel-Lindau syndrome." (PMID 35838801, 2022). "A total of 55 patients with MEN1-associated insulinoma were included, including 29 (52.7%) men and 26 (47.3%) women." (PMID 35698198, 2022). "Here, we report a case of MEN1 associated with insulinoma, parathyroid, and pituitary tumors by 68Ga-DOTATATE positron emission tomography/computed tomography (PET/CT)." (PMID 36042606, 2022). "Surgery for MEN1-related insulinoma (4–8% of all insulinoma) is believed to be associated with good outcomes, especially in terms of hypoglycemia cure rate." (PMID 34885063, 2021). "The authors demonstrated that genetic ablation or administration of B7x antibody in Men1-deficient mice with insulinomas results in reduced islet cell proliferation and pNET development accompanied by increased T-cell infiltration." (PMID 34680266, 2021). "In insulinomas, mutations in MEN1, ATRX and DAXX that are often mutated in all PNETs occur in no more than 10 percent: 3%, 8% and 3%, respectively." (PMID 34737724, 2021). "Patients with the MEN1 familial tumor syndrome develop multiple endocrine tumors, such as insulinomas, and somatic mutations of human MEN1 are also common in various sporadic NETs, including those of the pancreas." (PMID 34199469, 2021). "In mice, loss of Men1 alone yields insulinomas with high penetrance but long latency period (80–100% incidence by ~1 year of age)." (PMID 34199469, 2021). "Mice with homozygotic loss of Men1 in β-cells exhibited earlier incidence of insulinomas than the heterozygotes." (PMID 34680266, 2021). "In MEN1 patients, it has also been shown that early onset pancreatic microadenomas with loss of heterozygosity (LOH) of MEN1 express glucagon, whereas more advanced hormone-secreting tumours in the same patients were predominantly insulinomas." (PMID 32348957, 2020). "Inactivating MEN1 mutations are an unequivocal cause of germline insulinoma in mouse and man9,10,32,33." (PMID 33060578, 2020). "In this cohort, 9 patients were diagnosed with MEN1, and the MEN1-associated functional PanNENs were well-differentiated insulinomas." (PMID 33204258, 2020). "Nine patients with insulinoma were finally diagnosed to have MEN1 according to the diagnostic criteria." (PMID 33204258, 2020). "Although MEN1 alterations are rare in insulinomas, an integrative analysis of whole-exome and RNA sequencing data showed that deregulation of genes encoding proteins functionally related to MEN1 play a major role in this tumor type." (PMID 30657883, 2019). "Medical therapy is often unsuccessful in patients with MEN1-associated insulinomas, with surgery being the treatment of choice." (PMID 31263451, 2019). "In contrast to sporadic insulinomas, which tend to occur after the age of 40, MEN1-associated insulinomas occur primarily in patients younger than 40 years-old, with many of these tumors arising in patients younger than 20 years of age." (PMID 31263451, 2019). "This was further confirmed by four whole-exome sequencing studies of sporadic insulinomas that found only rare (2%) MEN1 somatic mutations, but also a frequent hotspot (p.T372R) somatic mutation in the Yin Yang 1 gene." (PMID 30657883, 2019). "Sanger-directed sequencing on a peripheral blood sample revealed an MEN1 gene mutation, indicating pediatric insulinoma with MEN1 syndrome." (PMID 29921249, 2018). "In the current study, exome sequencing for three sporadic insulinomas identified two somatic nonsense mutations in MEN1 (c." (PMID 29435419, 2018). "Whole exome sequencing identified 55 rare somatic mutations among three insulinoma patients, including MEN1 gene nonsense mutations (c." (PMID 29435419, 2018). "Among them, mutations in MEN1 were most related to the pathology of insulinoma, which provides evidence for use in early disease screening and target treatment of insulinoma." (PMID 29435419, 2018).
insulinomas (continued). "Two somatic functional mutations outside the MEN1 gene were identified in the pancreatic insulinoma by WES." (PMID 28969599, 2017). "A variety of functioning GEP NETs are associated with MEN1, most frequently gastrinomas (in 40% of patients) or insulinomas (10%), less frequently VIPomas, somatostatinomas and glucagonomas." (PMID 28965289, 2017). "Inactivation of both MEN1 alleles has been found in multiple endocrine tumors, including parathyroid adenoma, insulinoma, and a small subset of pituitary adenomas." (PMID 27175596, 2016). "To test the role of ARC in the development of insulinomas, we bred Pdx1-Cre; Men1 f/f mice with mice in which the gene encoding ARC had been deleted in the germ line to create mice lacking both menin and ARC in all cells of the pancreas." (PMID 26709830, 2015). "For example, metastases are present in up to 50% of patients with MEN1-associated insulinomas, whereas <10% of non-MEN1 insulinomas metastasise." (PMID 23933118, 2014). "Some patients with MEN1-associated tumors, such as parathyroid carcinoma and insulinoma, have both germline and somatic MEN1 mutations, consistent with Knudson’s two-hit hypothesis." (PMID 41736142, 2026). "Moreover, studies also reported that Men1 deficiency leads to nuclear translocation and activation of β-catenin in mouse insulinoma." (PMID 40837414, 2025). "A total of 10% of insulinomas are associated with MEN1, and overall, 10% are malignant." (PMID 41199767, 2025). "In two cases, pNEC was identified in patients with functional pNETs (one case with insulinoma-like neuroendocrine carcinoma, and one case with gastrinoma associated with MEN1 that developed postoperative distant metastases), the rest being in the group of patients with non-functional pNETs." (PMID 39941198, 2025). "Insulinomas are rare pancreatic neuroendocrine tumors (PNETs) that are typically benign, but their behavior can differ when associated with multiple endocrine neoplasia type 1 (MEN1)." (PMID 40406452, 2025). "Most insulinomas are sporadic, and only 5%–10% occur in association with MEN1." (PMID 40406452, 2025). "Genetic testing revealed that insulinoma was associated with MEN1 in 49 cases (35.3%)." (PMID 40941664, 2025). "In MEN1 insulinomas (N = 77), the rate of associated PHP was 78%." (PMID 38928056, 2024). "The studies’ overview (n = 7) showed cohorts that primarily included patients with MEN1-related insulinomas (n = 2) or MEN1-associated primary hyperparathyroidism (n = 2) or analyses of genetic testing in MEN1 (n = 3), a wide spectrum of objectives being registered across these data." (PMID 38928056, 2024). "About 10% of individuals with MEN1 mutation develop insulinoma." (PMID 36830839, 2023). "Apart from the MEN1 gene, only few genes are known to cause insulinoma." (PMID 37152923, 2023). "It has also been reported that MAFA missense mutation drives the development of familial insulinomatosis, characterized by the synchronous and metachronous occurrence of insulinomas, multiple MEN1-associated insulinoma precursor lesions and the rare development of metastasis." (PMID 36830839, 2023). "Herein, we report a rare case of MEN1 associated with insulinoma due to intermittent hypoglycemia for more than 1 year, and without a family history, which was successfully diagnosed by means of a novel tool of 68Ga-DOTATATE PET/CT after negative 18F-FDG PET/CT." (PMID 36042606, 2022). "The mean size of resected tumors in our study was similar compared to other cohorts of young patients with MEN1-associated insulinomas, but we had a higher rate of postoperative recurrence, which may be related to the selection of surgical options." (PMID 35698198, 2022). "In the same study, the authors tested the effect of a 4-week treatment with the Hh signaling inhibitor GDC-0449 (SMO inhibitor) on 8-month-old Men1-mutated mice with insulinomas, showing a reduction of proliferation of beta cells of approximately 60% and a reduction of circulating levels of insulin." (PMID 33919851, 2021).
insulinomas (continued). "All of the MEN1-associated functional PanNENs were insulinomas (6 single and 3 multiple)." (PMID 33204258, 2020). "Indeed, Meg3 and c-MET levels are described to be inversely correlated, both in MEN1-associated PanNENs and sporadic insulinomas." (PMID 32537434, 2020). "Indeed, MEN1, type-1 multiple endocrine neoplasm, represents the most frequent predisposition gene for insulinoma." (PMID 33101198, 2020). "Our results extend the growing list of pathogenic MEN1 mutations in sporadic cases of insulinoma." (PMID 29435419, 2018). "Our results showed that MEN1 mutations were found in two of the three insulinoma patients, which provided further evidence that MEN1 might be an important factor in the pathological process of insulinoma." (PMID 29435419, 2018). "WES revealed two somatic functional variants outside the MEN1 gene in the pancreatic insulinoma." (PMID 28969599, 2017). "Despite attempting to exclude MEN1 subjects, we nevertheless find widespread abnormalities in genes functionally related to MEN1, revealing a previously unsuspected unifying mechanism underlying insulinoma." (PMID 28974674, 2017). "Insulinoma may arise either due to loss of heterozygosity (LOH) of the chromosome region 11q13 or due to presence of various mutations in the MEN-1 gene in accordance with the Knudson’s hypothesis on cancer." (PMID 26307114, 2015). "The study identified presence of novel pathogenic MEN1 mutations in sporadic cases of insulinoma." (PMID 26307114, 2015). "Collectively, the deletion of β-catenin could effectively inhibit menin deficiency-driven β-cell proliferation and significantly improve the insulinoma-induced severe hyperinsulinemia and hypoglycemia in Men1-deficient mice." (PMID 25517963, 2014). "Therefore, a link between breast cancer and MEN1 may not necessarily be directly related to a pathogenic MEN1 variant but rather to an MEN1 clinical manifestation such as prolactinoma, hyperparathyroidism, or insulinoma." (PMID 36325452, 2022). "Finally, IGF2 overexpression was also detected in Men1-mutated mouse insulinoma." (PMID 33101198, 2020). "Additionally, MEN1 mutations are more common in insulinomas in children than in adults." (PMID 29921249, 2018). "Similarly, it would be informative to compare these non-MEN1 insulinomas to the whole-exomes and transcriptomes of bona fide MEN1-associated insulinomas, to elucidate which features the two different types of tumors share on their passage from normal beta cell to adenoma." (PMID 28974674, 2017). "Thus, surprisingly, despite having largely excluded MEN1-associated insulinomas, the strongest recurrent mutational signal nonetheless arose from genes encoding epigenetic modifiers functionally related to MEN1, which also encodes an epigenetic modifying enzyme." (PMID 28974674, 2017). "Malignant insulinomas in the context of MEN1 are extremely rare but present a clinical challenge due to their high propensity for recurrence, both locally and at distant sites, even after seemingly complete surgical resection." (PMID 40406452, 2025). "Considering the association of these two endocrine tumors, the patient received a clinical diagnosis of MEN1 and underwent surgical resection of the insulinoma and drug treatment of the prolactinoma with cabergoline at a dose of 0.75 mg/week." (PMID 40136120, 2025). "We present the case of a 58-year-old male with MEN1 who developed a malignant insulinoma in the pancreatic tail, which recurred in the pancreatic head, highlighting the complexities of managing insulinomas in the context of MEN1." (PMID 40406452, 2025). "If MEN1 involves the pancreatic islets, it can cause gastroenteropancreatic neuroendocrine tumors (GEP-NETs) such as insulinoma, gastrinoma, glucagonoma, VIPoma, or somatostatinoma." (PMID 40144450, 2025).
insulinomas (continued). "This case highlights the clinical challenge of managing malignant insulinomas in MEN1, emphasizing the importance of long-term follow-up and staged surgical interventions due to the high risk of recurrence." (PMID 40406452, 2025). "It is also possible that insulinomas in the context of MEN1 are manifesting earlier in life, possibly because of genetic or environmental factors that influence tumor development at a younger age." (PMID 40941664, 2025). "The tumor in our patient was a malignant, recurrent, solitary insulinoma measuring 3 cm, occurring in the context of MEN1." (PMID 40406452, 2025). "Our patient presented with a clinical picture highly suggestive of an insulinoma, with a history of MEN1 and a functional insulinoma." (PMID 40406452, 2025). "Regarding the newly introduced but less readily available 111In‐Exendin‐PET/CT, 7/56 (12.5%) CoEs have the ability to perform it in‐house and use it specifically for MEN1‐related insulinoma." (PMID 39587981, 2025). "In patients with MEN1, insulinomas have a higher likelihood of being malignant and recurrent, posing significant clinical challenges." (PMID 40406452, 2025). "In 2019, in the context of MEN1, he was diagnosed with an insulinoma in the pancreatic tail and underwent partial pancreatectomy." (PMID 40406452, 2025). "Approximately 20% of MEN1 patients develop NETs as their first symptom, which can appear as early as age 5 (e.g., insulinoma)." (PMID 39201946, 2024). "For our young male patient, pancreas was the initial sign of MEN1, followed by the discovery of Insulinoma and primary hyperparathyroidism." (PMID 39371924, 2024). "MEN1-NET studies (n = 7) included MEN1-related insulinomas (n = 2) or MEN1-associated PHP (n = 2) or analyses of genetic profile (n = 3), for a total of 877 MEN1 subjects." (PMID 38928056, 2024). "Insulinomas are detected in roughly 20% of MEN1 patients, serving as the initial clinical sign in about 10% of cases." (PMID 39201946, 2024). "Another study on 17 subjects with MEN1-related insulinomas showed that the median age at diagnosis was 31.5 years in genetically confirmed cases (N = 7) and 69 years in the subgroup without genetic confirmation (N = 10)." (PMID 38928056, 2024). "Functioning PanNETs in patients with MEN1 include insulinomas (10%), rarely gastrinomas, glucagonomas (<1%), somatostatinomas (1%), and vasoactive intestinal peptide-secreting tumors (VIPomas) (<1%)." (PMID 38893191, 2024). "Recent data showed that hypercalcemia in patients with insulinoma in MEN1 influences the insulin pattern of secretion." (PMID 38928056, 2024). "Insulinomas were the most frequent PanNETs in the juvenile (<21 years old) MEN1 GTE cohort and can be diagnosed even at five years of age." (PMID 38893191, 2024). "MEN1-derivate insulinomas (N = 72 subjects) were analyzed in relationship with their outcome and the co-presence of primary hyperparathyroidism across two studies." (PMID 38928056, 2024). "Our cohort included two MEN1-related insulinomas: one of them showed strong expression of GLP-1R, and the other one lacked the expression of GLP-1R." (PMID 37894845, 2023). "There are also several independent β cell-specific Men1 knockout mice that develop functional insulinomas." (PMID 37679316, 2023). "According to recent studies on sporadic insulinoma, YY1 (T372R) mutation is predominant (30%) but somatic MEN1 mutations occur rarely (7%)." (PMID 36830839, 2023). "The major limitation of this study was the small number of patients with metastatic or MEN1-related insulinomas." (PMID 37894845, 2023). "Even though all individuals in family 2 who participated in the study had PHPT, they also had other endocrine tumors that are part of the clinical condition of MEN1, such as pituitary adenomas secreting prolactin and GH, insulinoma, and adrenal tumors." (PMID 36967793, 2023). "In pediatric insulinomas, aneuploidy of chromosome 11 and other chromosomes have been found to be common in both MEN1 and non-MEN1 patients." (PMID 37152923, 2023).
insulinomas (continued). "Herein, we describe a 32 year old woman with long history of prolactinoma and secondary ammonhrea presented with not-severe manifestation of hypoglycemia due to concomitant presence of insulinoma with AIMAH leading to 12 years delay of MEN1 diagnosis." (PMID 35448982, 2022). "The mean age at diagnosis of MEN1 and insulinoma in our patients was similar to that reported in studies." (PMID 35698198, 2022). "Among the 55 patients with MEN1-related insulinoma, the mean age at the first episode of HH was 30.76 ± 14.03 years (range 9–75 years), and that at the time of diagnosis of insulinoma and MEN1 was 34.49 ± 14.99 and 36.20 ± 14.08 years, respectively." (PMID 35698198, 2022). "In our cohort, 19 (34.5%) patients presented with initial symptoms of hypoglycemia before the age of 22 years, and the mean age at diagnosis of insulinoma and MEN1 was 19.89 ± 5 and 22.95 ± 5.79 years, respectively." (PMID 35698198, 2022). "Mice heterozygous for the deletion of exon 3 of the Men1 gene exon 3 (Men1T/+), develop insulinomas (β cell tumors) from the age of 12 months, which closely resemble their cognate human tumors." (PMID 36428573, 2022). "Key learning points are to have a low index of suspicion for an insulinoma when there is a history of MEN1 and the need for a pragmatic approach to diagnosis and treatment during pregnancy." (PMID 37908256, 2022). "“MEN1” and “insulinoma” were used when searching the Peking Union Medical College Hospital (PUMCH) medical record retrieval system to obtain clinical information about patients." (PMID 35698198, 2022). "This case demonstrates that 68Ga-DOTATATE can be used for the detection of MEN1-related tumors and preoperative localization of small and low-grade insulinomas by PET/CT." (PMID 36042606, 2022). "With regards to the most common genes that mutate in pancreatic neuroendocrine neoplasms (panNENs) (MEN1, ATRX and DAXX) only loss of ATRX was detected in insulinoma sample." (PMID 34737724, 2021). "Others recently demonstrated greatly accelerated formation of low-grade (G1/G2) insulinomas in mice with targeted inactivation of both Men1 and Pten, with an onset of pNETs at 7 weeks of age." (PMID 34199469, 2021). "It is worth mentioning that similar changes were observed in mouse Men1 insulinomas and mouse Men1 mammary lesions." (PMID 34446068, 2021). "Again, in a larger cohort of patients, we showed that insulinoma is the most frequent functional tumor in Polish patients with MEN1-related PNETs." (PMID 34122352, 2021). "Given the typical genetic background (e.g. MEN1 loss), the secretion of insulin, the slow growth rate and the rarity of metastases, the MEN1 knockdown model should be regarded as the best available in vivo model for insulinoma." (PMID 34794032, 2021). "Although insulinomas are usually sporadic, they account for 10–30% of the functioning PNENs in patients with MEN1." (PMID 33672085, 2021). "In conclusion, GDC-0449 was shown to effectively suppress both proliferation of MEN1 tumor beta cells in vivo and reduce insulin secretion by insulinomas, revealing itself to be a promising therapy against MEN1 insulin-secreting pNETs." (PMID 33919851, 2021). "Approximately 2–10% of patients with insulinomas have multiple tumors, particularly those with MEN1." (PMID 33672085, 2021). "The hypermethylation of MGMT promoter has been described in about 40% of sporadic pNETs, 44.7% of MEN1 NF-pNETs, and only 8.3% of MEN1 insulinomas." (PMID 33919851, 2021). "Regarding hormone production, gastrinoma is the most frequent functional tumor in MEN1, whereas insulinoma dominates in TSC." (PMID 34122352, 2021). "The analysis of four patients with exon 5 revealed that 75% of them had insulinoma, and 50% of them were diagnosed during regular follow-up as family members of proband diagnosed with MEN1." (PMID 34122352, 2021).